CALR (calreticulin)
Diseases named in the same sentence as CALR in open-access papers (continued):
Sharing a sentence is not in itself a finding about the gene and the disease.
breast carcinoma (48 papers, 2005 to 2026). "Higher levels of calreticulin have been reported in various types of cancers and are associated with clinical stages and metastasis in breast cancer, gastric cancer, prostate cancer, and ovarian cancer." (PMID 30974841, 2019). "Calreticulin overexpression was also found to be associated with a higher risk of developing invasion and metastasis in breast cancer patients." (PMID 27418879, 2016). "Furthermore, as marker of ER stress, CALR is associated with enhanced immune response in breast cancer and systemic lupus erythematosus." (PMID 40019270, 2025). "In addition, calreticulin has been suggested to be a potential biomarker for breast cancer prognosis as its expression was associated with more advanced tumors." (PMID 27418879, 2016). "In cancers such as colorectal cancer (CRC), breast cancer (BC), and myeloproliferative neoplasms, reduced expression of calreticulin has been linked to compromised APP." (PMID 40075727, 2025). "Treatment with VAE resulted in phosphorylation of eIF2α in all cancer cell lines tested and increased calreticulin (CRT) exposure on the surface of pre-apoptotic SKBR3 breast cancer and B16F10 mouse melanoma cells." (PMID 40369535, 2025). "Studies indicate that elevated CALR expression in breast cancer can enhance tumor cell metastasis and resistance to chemotherapy." (PMID 40928500, 2025). "ENPP2 is involved in the clinical progression of breast carcinoma, and CALR exerts pro-tumor activities that are consistent with its effects on gene expression, cell proliferation, and immune response." (PMID 39201614, 2024). "In another in vitro study, recombinant T. solium calreticulin (rTsCRT) either alone or in combination with 5-fluorouracil inhibited the growth of the breast cancer cell line (MCF7) by interacting with scavenger receptors." (PMID 39367471, 2024). "That study concluded that translocated/externalized natural T. cruzi Calreticulin (nTcCRT) played a significant role in the anti-mammary tumor effect during experimental T. cruzi infection." (PMID 39367471, 2024). "The effect of ad-CALR and/or miR206 on the growth of breast cancer stem cells was determined by MTT assay." (PMID 36136972, 2022). "We observed that the significantly suppression effect on CALR expression in breast cancer stem cells when the cells were exposed to 50nM of miR-206 mimics for 48 or 72 hours." (PMID 36136972, 2022). "MiR-206 mimics significantly suppressed the protein and mRNA expression level of CALR in breast cancer stem cells in a dose-dependent manner." (PMID 36136972, 2022). "Our results showed that miR-206 mimics suppressed CALR expression, inhibited the proliferation and metastasis ability of breast cancer stem cells and finally induced cellular apoptosis." (PMID 36136972, 2022). "The results showed that miR-206 can significantly inhibit the growth of breast cancer stem cells, but the effect of miR-206 on the growth of breast cancer stem cells was significantly attenuated by overexpression of CALR." (PMID 36136972, 2022). "CALR expression in breast cancer stem cells was significantly increased in Ad-EVI-1 group, as compared to the control group; while knockdown of EVI-1 (si-EVI-1) effectively reduced CALR expression in breast cancer stem cells (P<0.05)." (PMID 36136972, 2022). "Taken together, miR-206 suppresses the growth and metastasis ability of breast cancer stem cells via blocking CALR expression." (PMID 36136972, 2022). "Studies have confirmed that calreticulin expression was up-regulated and mainly localized in the cytoplasm in breast cancer MDA-MB-231 stem cells." (PMID 36136972, 2022). "Our result not only clarified the mechanism of miR-206 regulating CALR expression in breast cancer stem cells, but also provided a novel target for the prevention and treatment of breast cancer." (PMID 36136972, 2022). "Overexpression of CALR enhanced the ability of breast cancer stem cells, and the invasive cells were increased to 127.7%, (p<0.05)." (PMID 36136972, 2022).
breast carcinoma (continued). "Our results suggest that enhancing the expression of miR-206 can significantly inhibit CALR expression in breast cancer stem cells." (PMID 36136972, 2022). "Our results indicated that miR-206 altered regulation of E-cadherin and N-cadherin through CALR-dependent manner in breast cancer stem cells." (PMID 36136972, 2022). "On the contrary, CALR expression was significantly decreased in T11 cells (genetically engineered mouse models (GEMM) of mammary cancer with overexpression of murine APOBEC3) that responded to anti-PD-1 treatment." (PMID 35418980, 2022). "Our research mainly focused on the bioinformatics analysis of CALR expression and potential molecular mechanism in tumors, and we only verified the CALR expression in breast cancer cell lines in vitro." (PMID 34910788, 2021). "For example, overexpression of CALR has been found in breast cancer, bladder cancer, PRAD, gastric cancer, hepatocellular carcinoma, colon cancer, pancreatic cancer, melanoma, esophageal cancer and leukemia." (PMID 34910788, 2021). "Among the five most common human tumors, CALR is correlated with 4 kinds of immune cells in breast cancer and colon cancer (p<0.05)." (PMID 34910788, 2021). "In breast cancer cells, cycle, apoptosis, the formation of G4 structures, calreticulin and high mobility group box 1 (HMGB1), as well as T cell activation, were analyzed by flow cytometry and adenosine triphosphate (ATP) by luminescence." (PMID 31731707, 2019). "Results from protein profiling revealed differential calreticulin expression patterns between tumoral and normal adjacent tissues of breast cancer specimens." (PMID 27418879, 2016). "In the present study, the characterization of calreticulin expression in breast cancer tissues shows the potential significance of its expression in the stroma." (PMID 27418879, 2016). "Calreticulin is able to prevent the anti-metastatic effects of estrogen receptor α (ERα) in breast cancer, induce cell migration and wound healing, as well as affect apoptosis through the regulation of calcium stores of the cell." (PMID 27418879, 2016). "This study shows that calreticulin expression in breast cancer is correlated with the degree of invasiveness; especially when stromal expression is considered." (PMID 27418879, 2016). "Our results demonstrate that the level of calreticulin expression in breast cancer is directly correlated with the invasiveness of the malignant lesions; represented by tumor stage/grade." (PMID 27418879, 2016). "Then we focused on evaluating the possible correlations between calreticulin expression and the conferment of an invasive phenotype in breast cancer cells as well as clarifying the related mechanisms." (PMID 27418879, 2016). "In breast cancer, calreticulin expression has been correlated with more advanced disease and a higher chance for the development of distant metastasis." (PMID 27418879, 2016). "To confirm our protein profiling results and characterize the histological pattern of calreticulin expression, we applied IHC on a range of breast cancer specimens with varying degrees of invasive potential." (PMID 27418879, 2016). "The proteomic component of the present study revealed calreticulin as differentially expressed in various invasive states of breast cancer." (PMID 27418879, 2016).
breast carcinoma (continued). "The present study focused on the identification and evaluation of calreticulin (CRT) as a potential biomarker for breast cancer invasion." (PMID 27418879, 2016). "Translocated/externalized native Trypanosoma cruzi calreticulin is responsible for at least an important part of the anti mammary tumor effect of the experimental infection with this parasite." (PMID 27619675, 2016). "For example, serum levels of Calreticulin have been shown to increase in patients with rheumatoid arthritis and increased levels of Calreticulin have been reported in breast cancer, gastric cancer, and lung cancer." (PMID 24134804, 2013). "Accumulation of CALR protein is observed in a few cancers, including breast cancer and hepatocellular carcinoma." (PMID 15870709, 2005). "Additionally, hydatid cyst fluid antigens have been reported to exert cytotoxic effects against both the MDA-MB-231 and 4 T1 mouse breast cancer cell lines, while calreticulin derived from T. solium has demonstrated similar effects on the MCF-7 cell line." (PMID 40247360, 2025). "CALR is overexpressed in breast cancer, and its knockdown can affect the spread of the tumor." (PMID 39479348, 2024). "Interestingly, both the native and recombinant forms of T. cruzi calreticulin showed an anti-mammary tumor capacity in vivo." (PMID 39367471, 2024). "In this study, we investigate the potential mechanism of miR-206 affecting the biological activity of breast cancer stem cells by interfering with the expression of CALR, and then providing novel targets and new strategy for the prevention and treatment of breast cancer." (PMID 36136972, 2022). "Our study demonstrated that enhancing the expression of EVI-1 could significantly enhance the expression of CALR in breast cancer stem cells, and there was a significant positive correlation between CALR and EVI-1." (PMID 36136972, 2022). "Similarly, HIF-1 can directly activate calreticulin (CALR) transcription and facilitate breast cancer progression by promoting the BCSC phenotype in hypoxic." (PMID 36046046, 2022). "Our results suggested that miR-206 could significantly inhibit the invasion ability of breast cancer stem cells, whereas the ability of miR-206 to inhibit the invasion of breast cancer stem cells is reduced by overexpression of CALR." (PMID 36136972, 2022). "The breast cancer stem cells were transfected with Ad-CALR in combination with miR-206 mimics for 48 hours, the inhibitory effect of miR-206 was reversed by overexpression of CALR." (PMID 36136972, 2022). "We also conjugated to an antibody we previously raised against the N-terminal of the calreticulin protein, a biomarker expressed by colorectal and breast cancer cells, to produce targeted NCs (anti-CRT-AuNCs), and demonstrated their binding to cancer cell lines in 2D." (PMID 39872615, 2022). "We verified the expression of CALR in breast cancer cell lines by vitro experiments." (PMID 34910788, 2021). "In the present study, we showed that oleandrin treatment triggered breast cancer cell ICD by inducing calreticulin (CRT) exposure on cell surface and the release of high-mobility group protein B1 (HMGB1), heat shock protein 70/90 (HSP70/90), and adenosine triphosphate (ATP)." (PMID 33762577, 2021). "Besides confirming calreticulin overexpression in invasive breast cancer tissues, this study reveals a calreticulin-dependent pro-invasive potential and suggests possible contributing pathways." (PMID 27418879, 2016). "In addition, the calreticulin-mediated acetylation system, which uses polyphenolic acetates and acetyl CoA as acetyl group donating molecules, is utilized for the treatment of breast cancer." (PMID 26125438, 2015). "Down-regulation of CALR was recently observed in a melphalan-resistant MCF-7 breast cancer cell line, suggesting that it might be important in the development of resistance." (PMID 17477866, 2007).
breast carcinoma (continued). "Thus, overexpression of CALR could effectively attenuate the cytotoxic effect of miR-206 in breast cancer stem cells." (PMID 36136972, 2022). "Furthermore, calreticulin confers a more invasive breast cancer phenotype." (PMID 27418879, 2016). "Immune‐related proteins osteopontin, lactotransferrin, calreticulin, and peroxiredoxin 2 were selected as potential biomarkers of MDSC‐producing breast cancer." (PMID 39939411, 2025). "Collectively, these results suggest that ADSC-EVs markedly inhibit the expression of TubA1 and CALR, contributing to the reduced viability and migration of MCF-7 breast cancer cells." (PMID 41514893, 2025). "The recombinant human milk peptide lactaptin RL2 induced calreticulin exposure, ATP and HMGB1 release in breast cancer cells and promoted the phagocytosis of dying-cancer cells by macrophages." (PMID 38077402, 2023). "Silencing CD47 also downregulated MTT-based viability, whereas it significantly suppressed CALR-induced tumor inhibition in U2OS OS cells, TT2 OS cells, MDA-MB-231 breast cancer cells, and PANC1 pancreatic cells." (PMID 36943734, 2023). "Aim to investigate the effect of miR-206 on the growth and metastasis of breast cancer stem cells and clarify the precise mechanism of miR-206 on EVI-1-mediated CALR expression in driving malignant phenotype." (PMID 36136972, 2022). "In particular, a high CALR expression has been correlated with poor outcomes in gastric carcinoma, NSCLC, breast carcinoma, pancreatic cancer, neuroblastoma, bladder carcinoma, and mantle cell lymphoma." (PMID 36338983, 2022). "On 4T1 breast cancer cells, BP-PTT modulates the most crucial markers of ICD, namely, exposure of calreticulin (CRT) and release of high mobility group box-1 (HMGB-1) and ATP." (PMID 35844506, 2022). "In the breast cancer cell line MCF7, P4 elicits changes in the expression of S100A11, S100A10, calreticulin, VDAC1, SERCA3, and SERCA1, resulting in a barely Ca2+ efflux from the endoplasmic reticulum as well as impaired membrane potential in the mitochondria." (PMID 33076541, 2020). "Calreticulin also increased 3.48-fold and 3.07-fold in MDA-MB-231 and ZR-75-1 breast carcinoma cells, respectively, and 4.27-fold and 4.28-fold in the lung tumor cell lines, respectively." (PMID 27893426, 2016). "Besides, HIF-1 can directly activate the transcription of calreticulin (CALR) in cancer cells to induce Wnt/β-catenin signal transduction, which exert effect on promoting the phenotype of CSCs in breast cancer." (PMID 38561775, 2024). "Furthermore, PKHB1-induced cell death exhibits key molecular hallmarks of ICD, including the exposure of calreticulin, HSP70, HSP90, and the release of ATP and HMGB1 in various leukemic and breast cancer cell lines." (PMID 38077402, 2023). "The mRNA and protein levels of CRM-1 and CALR were higher in breast cancer cells lacking ERα compared with those that express Erα." (PMID 35804555, 2022). "There is a positive correlation of CALR and EVI-1 in breast cancer stem cells." (PMID 36136972, 2022). "Specifically, CALR expression was significantly increased in CT26 cells (murine colorectal cancer) that responded to anti-CTLA and anti-PD-1 treatment, and CALR expression was obviously increased in EMT6 cells (murine breast cancer) that responded to anti-PD-1 treatment." (PMID 35418980, 2022).
melanoma (47 papers, 1999 to 2026). A malignant, usually aggressive tumor composed of atypical, neoplastic melanocytes. "Here, we demonstrate that 8-MOP plus UVA light reduces melanoma cell viability along with the emission of ICD-associated danger signals including calreticulin (CALR) exposure on the cell surface and secretion of ATP, high mobility group box 1 (HMGB1) and type I interferon (IFN)." (PMID 31371700, 2019). "Here we describe the ICD mechanism of lepadin A by proving the translocation of the protein calreticulin (CRT) to the plasma membrane of human A2058 melanoma cells." (PMID 37779162, 2023). "A most recent study revealed that B16 melanoma cells release externalized calreticulin (ExoCRT) during severe ER stress, which is subsequently recognized by the NKp46 receptor on NK cell membrane." (PMID 38106991, 2023). "Peptide Rb4, derived from protein proteolipid protein 2 (PLP2), acts directly on tumor cell multiplication inducing the expression of two DAMPs molecules, HMGB1 and calreticulin, which trigger immunoprotective effects in vivo against melanoma cells." (PMID 36012593, 2022). "We have previously identified constitutive DAMPs (HMGB1 and Calreticulin) as well as new putative inducible DAMPs such as Haptoglobin (HP), from a therapeutically used heat shock-conditioned melanoma cell lysate (called TRIMEL)." (PMID 35805888, 2022). "Since cell-surface expression of calreticulin is important for recognition by dendritic cells, the increased expression of calreticulin would also be consistent with an elevated anti-melanoma cell immune response to irradiated cells." (PMID 33789714, 2021). "Calreticulin, another ER-residing stress protein present on tumor cell membranes, was shown to induce migratory capacity in melanoma cells." (PMID 32443761, 2020). "In vitro studies in B16F10 murine melanoma cells showed an increase in calreticulin translocation after therapy, and in vivo studies noted an increase in TNF-α and IL-6 as well as an increase in activated T cell infiltration into primary and metastatic tumors." (PMID 33260534, 2020). "Application of anti-calreticulin antibodies significantly reduced laminin-dependent spreading of melanoma cells." (PMID 32443761, 2020). "In vitro experiments conducted with B16F10 melanoma cells showed an increase in calreticulin and HSP70 expression." (PMID 33260534, 2020). "To test the effects of pro-phagocytic signal expression on phagocytosis, we exposed B16 melanoma cells to doxorubicin (0.03 μM) for 24 hours and demonstrated induction of the pro-phagocytic signals calreticulin and phosphatidylserine (PS)." (PMID 31205227, 2020). "This correlates with immunogenic cancer cell death and higher calreticulin and heat‐shock protein 90 expressions induced by gas plasma treatment in melanoma cells." (PMID 32440479, 2020). "In this regard, in a previous study, we have shown that HS conditioning is able to induce the secretion of the DAMP protein HMGB1 by melanoma cells as well as the mobilization of CALR to plasma membrane, a well-known “eat me” signal for phagocytic cells." (PMID 29744371, 2018). "Moreover, we have also reported that the HS conditioning of melanoma cells belonging to the lysate increased Calreticulin (CRT) plasma membrane translocation and induced the release of HMGB1." (PMID 35805888, 2022). "We also noted a substantial increase in cell surface expression of calreticulin in human SK-MEL-28 melanoma cells, and especially in the IGR39 cell line that is known to be BRAF inhibitor tolerant and displays gene expression signatures linked to immunotherapy resistance." (PMID 33789714, 2021). "Two schweinfurthin compounds differentially reduced the growth of human and murine melanoma cells in vitro and induced plasma membrane surface localization of the ER-resident protein calreticulin in B16.F10 melanoma cells, an indicator of immunogenic cell death." (PMID 30400835, 2018).